TIMP3 (TIMP metallopeptidase inhibitor 3)
Diseases named in the same sentence as TIMP3 in open-access papers (continued):
Sharing a sentence is not in itself a finding about the gene and the disease.
diabetic nephropathy (16 papers, 2013 to 2025). "Deficiencies in TIMP3 worsen diabetic renal injury, characterized by mesangial dilation and increased microalbuminuria, and affecting the progression of diabetic nephropathy through changes to Akt, ERK1/2, and PKC signaling pathways." (PMID 38774282, 2024). "Another study has confirmed that TIMP-3 deficiency contributes to the development of diabetic nephropathy through FoxO1/STAT1 interactions." (PMID 38774282, 2024). "This review recapitulates the pathological, diagnostic and therapeutic potential roles of TIMP3 and the noncoding RNA (microRNA, long noncoding RNA) related to its expression, in the progression of diabetic nephropathy." (PMID 34181080, 2021). "• Loss of TIMP3 contributes to the onset and progression of diabetic nephropathy in human and mouse." (PMID 33634991, 2021). "ADAM17 and its inhibitor, TIMP-3, are involved in nephropathy, and the loss of TIMP-3 underlies the development of diabetic nephropathy via FoxO1/STAT1 interplay." (PMID 33419373, 2020). "The loss of TIMP3 can lead to diabetic kidney disease in both human and mouse via the interplay of FOXO1 and STAT1." (PMID 29796115, 2018). "Studies in patients have implicated a possible role of TIMP3 in diabetic nephropathy." (PMID 33634991, 2021). "To seek the mechanisms by which TIMP3 deficiency may worsen diabetic nephropathy we profiled STZ-WT and STZ-Timp3−/− kidneys by microarray analysis." (PMID 23401241, 2013). "Our study suggests that loss of TIMP3 is a hallmark of DKD in human and mouse models and designates TIMP3 as a new possible therapeutic target for diabetic nephropathy." (PMID 23401241, 2013). "In the study of diabetic nephropathy, the HOXA-AS2/miRNA-302b-3p/TIMP3 axis has been determined to protect against inflammatory response and inhibit proliferation in podocytes, thereby mitigating the progression of diabetic nephropathy." (PMID 38311789, 2024). "Pimagedine targeting TIMP3 has been found to a beneficial effect in treating patients with diabetic nephropathy." (PMID 39221148, 2024). "According to earlier research, TIMP3 is essential for the development of chronic kidney illnesses, including renal carcinoma, diabetic nephropathy, chronic nephritis, and other kidney diseases." (PMID 38774282, 2024). "In a retrospective study, the potential roles of TIMP3 and its related noncoding RNA in the progression of diabetic nephropathy were investigated." (PMID 38774282, 2024). "Pimagedine targeting TIMP3 acts as an inhibitor of advanced glycation end products and is effective in managing diabetic nephropathy when used on its own or in conjunction with other treatments." (PMID 39221148, 2024). "Ablation of TIMP-3 in mice exacerbated the pathology in two different models of diabetic nephropathy, the streptozotocin-induced model and the Akita mouse." (PMID 35207132, 2022). "In agreement, Casagrande and colleagues demonstrated that Timp3-overexpression in myeloid cells protected mice from streptozotocin-induced diabetic nephropathy at the same extent as ablation of ADAM17 in podocytes." (PMID 35207132, 2022). "Several recent evidences point to TIMP3 as a potential biomarker or therapeutic target for kidney diabetic disease." (PMID 34181080, 2021). "Among them, Timp3 polymorphisms showed a significant association with diabetic nephropathy, suggesting that allelic variations of this gene may contribute to the risk of developing the disease and pointing at Timp3 as a susceptibility gene for DKD." (PMID 34181080, 2021). "However, recently MMP-2 and MMP-9, whose activity is regulated by TIMP3, were found to be able to induce epithelial–mesenchymal transition of tubular cells as well as endothelial–mesenchymal transition, both important mechanisms causing kidney fibrosis in diabetic nephropathy." (PMID 34181080, 2021). "TIMP-3 has been found to be down-regulated in diabetic nephropathy and increased TIMP-3 expression shows a renoprotective role for DN progression." (PMID 32046355, 2020).
diabetic nephropathy (continued). "Studies on kidney biopsies from patients with diabetic nephropathy confirmed a significant reduction in TIMP3, FoxO1 and FoxO1 target genes involved in autophagy compared to controls, while STAT1 expression was strongly increased." (PMID 23401241, 2013). "We identify similar changes in expression of human TIMP3 and FoxO1 in renal biopsies from patients with diabetic nephropathy." (PMID 23401241, 2013). "Overall, previous reports and our data indicate that rescuing TIMP3 functions may represent a new therapeutic approach to block the progression of diabetic nephropathy." (PMID 34181080, 2021). "• Exogenous TIMP3 peptides, specifically targeted to the kidney, may represent a therapeutic approach for the treatment of diabetic nephropathy." (PMID 33634991, 2021). "While further studies are needed to confirm the relevance of these results, it is intriguing to speculate that this specific metabolic signature might be explored as a companion biomarkers for TIMP3-based treatment of diabetic nephropathy." (PMID 34181080, 2021). "Thus we hypothesize that in a diabetic, metabolically stressed context the effect of TIMP3 deficiency on the FoxO-regulated autophagic pathway may contribute, through the ‘two-hit’ model, to attenuate the protective function of the autophagic process and hence worsen diabetic nephropathy." (PMID 23401241, 2013). "Thus, TIMP3 plays an important function in maintaining kidney homeostasis and represents a new protective candidate to be explored for controlling diabetic nephropathy." (PMID 23401241, 2013). "To investigate the molecular role of FoxO1 in the regulation of autophagy in diabetic nephropathy, we generated Timp3knockdown cells by stably transfecting SV40 MES13 cells with three shRNA plasmids that target different sequences in the Timp3 mRNA (T3kd MES13)." (PMID 23401241, 2013). "There is currently no specific therapy for diabetic nephropathy, and the ability to restore high TIMP3 activity specifically in the kidney may represent a potential therapeutic strategy for the amelioration of renal injury under conditions in which its reduction is directly related to the disease." (PMID 34181080, 2021).
Arthritis (15 papers, 2005 to 2025). Inflammation of a joint. "In conclusion, TIMP-3 is considered a valuable target for the therapy of conditions associated with enhanced proteolysis, including arthritis and cancer." (PMID 30279425, 2018). "Nevertheless, despite its wide inhibitory spectrum and thus its ability to inhibit additional metalloproteases mainly involved in arthritis, TIMP3 therapeutic use has limited application in clinics." (PMID 36013323, 2022). "Timp3-null mice subjected to antigen-induced arthritis display a dramatic increase in inflammation and higher levels of circulating TNF compared to wild-type controls." (PMID 35207132, 2022). "Ablation of TIMP-3 in mouse, and subsequent loss of ADAM17 inhibition, leads to arthritis, chronic hepatic inflammation, insulin resistance, and liver/heart failure due to excessive release of tumor necrosis factor (TNF)." (PMID 33673623, 2021). "Conversely, by targeting ADAM17, there is an overexpression of TIMP-3 dampened TNF-release that ameliorated the development of arthritis in a murine model of the disease." (PMID 33673623, 2021). "In the context of arthritis, α2M was found in similar concentrations as TIMP3 in the synovial fluid of joints and it rapidly bound to collagenase." (PMID 34268335, 2021). "Tissue inhibitor of metalloproteinase (TIMP)‐3 is a natural inhibitor of a range of enzymes that degrade connective tissue and are involved in the pathogenesis of conditions such as arthritis and cancer." (PMID 30450736, 2019). "TIMP-3 has proved beneficial in diseases characterized by enhanced proteolysis, including arthritis and cancer; thus, approaches to increase its bioavailability in the tissue have been developed for the therapy of such diseases." (PMID 30279425, 2018). "ADAMTS also play important roles in connective tissue organization, coagulation, inflammation, arthritis, angiogenesis, and cell migration and are regulated by the Tissue Inhibitor of Metalloproteinase 3 Gene (TIMP3)." (PMID 28415562, 2017). "Taking into consideration increased levels of TNF-α in patients with RA and the obvious effect of TNF-α neutralization for the alleviation of arthritis, our finding of a low incidence of antibodies against TIMP-3 is unexpected." (PMID 16207317, 2005). "Importantly, the protective role of TIMP3 in arthritis is well-documented, as it has been shown to suppress disease progression 56-58." (PMID 40765832, 2025). "As a result, the detection of active MMP-3, ADAMTS-5, and TIMP-3 in clinical samples could reveal information regarding the development of arthritis and the response to therapy." (PMID 37259405, 2023). "TIMP-3 plays a protective role in arthritis by inhibiting ADAM17, thereby dampening TNF signalling." (PMID 35207132, 2022). "TIMP-3 may be a suitable therapeutic treatment for patients with arthritis to suppress not only innate inflammatory cytokines in arthritis but also ADAMTS4 and ADAMTS5." (PMID 25606593, 2014). "Furthermore, Timp-3 knockout mice present with an increased inflammatory response to antigen-induced arthritis and increased aggrecan and collagen II degradation with age." (PMID 25606593, 2014). "More recently, a role for TIMP3 in promoting LRP1-based protease clearance raises the possibility of identifying peptides that promote both, the binding and clearance of destructive ADAMTS proteases in cartilage to modify disease progression in arthritis." (PMID 34268335, 2021). "In addition, -1Ala-TIMP-3 and T2G-TIMP-3 were able to inhibit the aggrecanases (ADAMTS-4 and -5) and block aggrecan degradation, which is, together with TNF release, a key feature of arthritis." (PMID 33579029, 2021).
myocardial infarction (15 papers, 2014 to 2025). Gross necrosis of the myocardium, as a result of interruption of the blood supply to the area, as in coronary thrombosis. "An imbalance between TIMP3 and MMPs/ADAMs/ADAMTSs causes various diseases, including myocardial infarction, Alzheimer’s disease, intervertebral disc degeneration, impaired cognitive function, and tumour metastasis." (PMID 38542164, 2024). "TIMP-3 also plays a therapeutic function in maintaining tissue integrity by acting as a protective factor against myocardial infarction, ischemia-associated cardiomyopathy, and heart fibrosis." (PMID 39195176, 2024). "It has been demonstrated that MMP-14 is upregulated in a particularly harmful macrophage phenotype (MMP14+TIMP3−), which contributes to increased risk for plaque rupture and myocardial infarction." (PMID 34702365, 2021). "Decreased levels of TIMP-3 have been linked to ventricular remodelling after myocardial infarction." (PMID 34702365, 2021). "Deficiency of TIMP3 can worsen cardiac remodeling and dysfunction after myocardial infarction (MI), which can be ameliorated by supply of TIMP3 through overexpression or recombinant protein." (PMID 37057103, 2023). "There have been reported that injecting the exogenous TIMP3 gene directly into the edge of myocardial infarction effectively limited scar enlargement, adverse ECM remodeling, and cardiac function decline." (PMID 40893347, 2025). "Tissue inhibitor of metalloproteinase 3 (TIMP3) was recently demonstrated capable to regulate some gene expression in a myocardial infarction model." (PMID 37057103, 2023). "Recent studies have evaluated the potential utility of recombinant TIMP3 in cardiovascular diseases and engineered TIMP3 molecules with an additional glycosylation site led to improved expression and cardiac function in a rodent model of myocardial infarction." (PMID 36430707, 2022). "MiR-17-92 cluster is able to induce cardiomyocyte proliferation in postnatal and adult heart as well as in response to myocardial infarction, which is partly caused by binding of miR-17 to 3’ UTR of Timp3 and suppressing Timp3 expression." (PMID 32612540, 2020). "This demonstrates the therapeutic potential of preserving the local equilibrium of TIMP-3 in the heart given its diverse functions in the modulation of different processes involved in adverse post-myocardial infarction remodeling." (PMID 33419373, 2020). "Studies have shown that after myocardial infarction, TIMP-3 improves remodeling and myocardial function, promoting angiogenesis and inhibiting early proteolysis." (PMID 33419373, 2020). "TIMP3 has been known to bind to the ECM with high affinity and decreased levels associated with after myocardial infarction." (PMID 30459952, 2018). "Furthermore, TIMP3 has been identified as a candidate biomarker for several diseases, including diabetic nephropathy, myocardial infarction, and cancer progression." (PMID 38542164, 2024). "This fast binding kinetics might be beneficial for intracoronary delivery of TIMP3 molecule during balloon angioplasty procedures for the treatment of acute myocardial infarction (AMI)." (PMID 30459952, 2018). "Our work therefore suggests that reducing MMP-14 activity and increasing that of TIMP-3 could be valid therapeutic approaches to reduce plaque rupture and myocardial infarction." (PMID 25301980, 2014). "Moreover, a recent study also showed that a miR-21-5p antagomir could repress myocardial fibrosis by targeting TIMP3 after myocardial infarction, which provided an important foundation for our research." (PMID 34722652, 2021). "Translational studies on the treatment of heart diseases such as myocardial infarction (MI) with TIMP3 replenishment suggest the therapeutic potential of TIMP3 in patients with heart failure." (PMID 32612540, 2020). "Following myocardial infarction (MI), TIMP3 levels are decreased in the infarct and peri-infarct myocardium." (PMID 32612540, 2020).
myocardial infarction (continued). "Therefore reducing MMP-14 activity and increasing that of TIMP-3 could be valid therapeutic approaches to reduce plaque rupture and myocardial infarction." (PMID 25301980, 2014). "Additionally, some reports propose that downstream target TIMP-3 is not only involved in the regulation of the matrix metalloproteinases but also is related to angiogenesis during the invasion and metastasis of cancer cells and the protection of myocardial infarction." (PMID 34948080, 2021). "Similarly, TIMP3 had a regulatory effect on apoptosis, angiogenesis, and ECM remodeling of myocardial infarction." (PMID 40893347, 2025). "Considerable data in experimental models have demonstrated a protective role of TIMP3 in coronary artery disease (CAD) and myocardial infarction (MI)." (PMID 36005441, 2022).
atherosclerosis (14 papers, 2014 to 2024). A disease characterized by the build-up of fatty material and calcium deposition in the arterial wall resulting in partial or complete occlusion of the arterial lumen. "Among TIMPs, TIMP-3 is closely associated with atherosclerosis, aneurysm, hypertension, and post-ischaemic neuronal injury, but its relationship with IS and ICH has not been confirmed." (PMID 35444693, 2022). "A similar correlation between insulin resistance, atherosclerosis and TIMP-3 expression was also observed in humans." (PMID 35207132, 2022). "MiR-181b is increased in human atherosclerotic plaques and abdominal aortic aneurysms (AAA), and inhibition of miR-181b suppressed the development and progression of atherosclerosis and aneurysms through increasing expression of TIMP3, elastin, and collagen." (PMID 32612540, 2020). "In patients with atherosclerosis, elevated TIMP3 levels in the plasma have been reported, but TIMP3 is reduced in carotid atherosclerotic plaques from patients with type 2 diabetes." (PMID 32612540, 2020). "Conversely, transgenic overexpression of TIMP-3 in mouse macrophages reduced atherosclerosis formation and improved markers of plaque stability." (PMID 25301980, 2014). "Consequently, the multifaceted role of TIMP-3 in atherosclerosis development suggests its involvement in modulating macrophage proliferation, emphasizing its significance beyond its conventional role in MMP inhibition." (PMID 39195176, 2024). "In addition to targeting inflammation, TIMP3 exerts its protective effect against atherosclerosis by regulating endothelial function and extracellular matrix remodeling." (PMID 36005441, 2022). "TIMP-3 overexpression decreased macrophage infiltration and the size of atherosclerotic plaques, indicating a protective role for the inhibitor in the development of atherosclerosis." (PMID 35207132, 2022). "However, this kind of protective effect was abolished when Timp3 was knocked out at the same time, revealing that miR-181b deteriorated atherosclerosis by suppressing TIMP-3 expression." (PMID 35548442, 2022). "The effect of TIMP-3 on the atherosclerosis, cardiogenic emboli and atrial fibrillation was weak." (PMID 35444693, 2022). "Conversely, by targeting the ADAM17/TNF axis, overexpression of TIMP-3 in mouse macrophages reduced adipose inflammation, insulin resistance, and nonalcoholic fatty liver disease, other than reducing atherosclerotic plaques in a mouse model of atherosclerosis." (PMID 33673623, 2021). "TIMP3 can counteract inflammation and atherosclerosis in mouse models; therefore, TIMP3 holds the potential as treatment for patients with atherosclerosis, although this requires further translational and clinical studies." (PMID 32612540, 2020). "In addition, we found the Mmp inhibitor Timp3 to be enriched in the insoluble fraction, which has been reported to protect against atherosclerosis." (PMID 29208753, 2018). "Although there is evidence for a protective role of Timp3 in atherosclerosis, Itih1 and Itih2 have not yet been associated with plaque development." (PMID 29208753, 2018). "Similarly, TIMP-3 overexpression in mouse macrophages reduced adipose inflammation, insulin resistance, nonalcoholic fatty liver disease, and atherosclerotic plaques in an atherosclerosis mouse model." (PMID 33673623, 2021). "Given that atherosclerosis is the pathophysiological mechanism of CAD and MI, our results corroborate the findings from the basic research showing a protective effect of TIMP3 on atherosclerosis." (PMID 36005441, 2022). "And inhibition of miR-712 by Anti-miR-712 has been shown to suppress atherosclerosis, inflammation, and AAA induced by angiotensin II (Ang II), implying a protective role for TIMP3 in these processes." (PMID 32612540, 2020). "TIMP3 and RECK have also been reported to mediate the inhibitory effects of interleukin-32α (IL-32α) on endothelial inflammation, smooth muscle cell activation, and atherosclerosis development." (PMID 32612540, 2020).
atherosclerosis (continued). "Although recent study showed that lack of TIMP3 increases inflammation and polarizes macrophages towards a more inflammatory phenotype resulting in increased atherosclerosis 50,51, the relationship between TIMP3 and MIF did not be detected in our study." (PMID 25661015, 2015). "Furthermore, the absence of TIMP-3 has been demonstrated to polarize macrophages and intensify inflammation in atherosclerosis, as evidenced in ApoE null mice." (PMID 39195176, 2024). "Since neither TIMP-1 nor TIMP-2 overexpression fully inhibited atherosclerotic plaque development, the protective role exerted by TIMP-3 may be mechanistically related to its ability to inhibit ADAM17 to regulate TNF release and other key processes in atherosclerosis development." (PMID 35207132, 2022).